RAC1 (Rac family small GTPase 1)
Diseases named in the same sentence as RAC1 in open-access papers (continued):
Sharing a sentence is not in itself a finding about the gene and the disease.
breast carcinoma (continued). "In addition, it has previously been shown that SNTA1/Grb2/p66Shc signaling complex enhances Rac1 activation that in turn augments metastatic characteristics of breast cancer cells." (PMID 35273919, 2022). "Likewise, clones with high migration potential also exhibited a lower RAC1b/RAC1 ratio than clones with low migratory activity, in accordance with earlier data from breast cancer cell lines." (PMID 35565186, 2022). "Based on the cross-talk of integrins and FAK and integrin-mediated regulation of the activity of Rho family proteins in cell migration, the expression of Rho family proteins, including Rac1, RhoA, Cdc42, and integrins, is detected in breast cancer cells after CuB exposure." (PMID 36362132, 2022). "In addition, in invasive breast cancer cells, ARF1 constitutively binds Rac1, a Rho GTPase associated with lamellipodia formation during cell migration." (PMID 35805075, 2022). "Indeed, KCTD5 is a negative regulator for the migration of melanoma and breast cancer cells, by affecting Rac1 activity and Ca2+ signaling." (PMID 34001146, 2021). "Moreover, in contrast to MIA PaCa-2 and PaTu 8988s they express readily detectable levels of RAC1b, an alternatively spliced isoform of RAC1 associated with the E subtype in both PDAC and breast cancer cells." (PMID 34572891, 2021). "In addition to endocrine resistance, PLAC8 regulates RAC1 levels, and another study has reported that RAC1 promotes breast cancer chemoresistance by influencing DNA damage repair." (PMID 34627411, 2021). "Furthermore, the Rac1(N17) dominant-negative mutant also showed that Rac1 inhibits cell proliferation of a highly aggressive and invasive MTLn3 breast cancer cell line." (PMID 32992837, 2020). "Besides, in HER2-positive breast cancers, high expression of RAC1 mRNA significantly correlated with poor prognosis of the patients." (PMID 31895772, 2020). "To further validate the correlation of Rac1 expression with breast cancer chemoresistance, we collected 133 core needle biopsies from breast cancer patients before neoadjuvant chemotherapy, which were then treated with platinum-based drugs, Taxanes, and Doxorubicin." (PMID 32193458, 2020). "We examined Rac1 expression in various breast cancer cell lines." (PMID 32193458, 2020). "Moreover, p66ShcA increases the migratory properties of prostate and breast cancer cells by its recruitment to focal adhesion complexes, thereby regulating Rac1-mediated actin remodeling." (PMID 31941526, 2020). "In this regard, up-regulated P-Rex1 levels in luminal breast cancer cells do not cause marked changes in basal Rac1-GTP but rather sensitize Rac1 activation to the stimulation of tyrosine-kinase receptors and GPCRs." (PMID 32092966, 2020). "The overexpression of the MCF2L gene, encoding guanosine conversion factor, could activate the key regulatory factors of the Rho GTP family (Cdc42 and Rac1) and promote tumor metastasis in breast cancer cells." (PMID 32089682, 2020). "Remarkably, RAC1 expression was discriminatory of good and bad prognosis in breast cancer patients." (PMID 33298895, 2020). "Interestingly, ZNF750 depletion resulted in a significant RAC1 upregulation in all the three breast cancer lines." (PMID 33298895, 2020). "The overexpression of the RAC1 gene in the breast cancer tissues has also been reported." (PMID 32104177, 2020). "Rac1 is also upregulated in chemoresistant breast cancer and correlates with poor prognosis." (PMID 33096815, 2020). "Importantly, ROC curve showed that high Rac1 level significantly distinguished chemoresistant cases from sensitive cases of the breast cancers patients." (PMID 32193458, 2020). "In the current study, we show that the axis ZNF750/RAC1 may function as a potential biomarker for predicting patient survival in breast cancer." (PMID 33298895, 2020).
breast carcinoma (continued). "Thus, we applied the siRac1/DDP NPs to mouse breast cancer cell 4T1, and found the similar effect of suppressing mouse Rac1 expression, as well as inducing DNA damage." (PMID 32193458, 2020). "We can see that the expression level of RAC1 is higher in breast cancer tissue." (PMID 33306680, 2020). "What counts is, this is probably done by affecting Rac1 because the western blot assay showed that derivative 4F could down-regulate Rac1 protein expression in breast cancer cells at a lower effective concentration than that for Rhein." (PMID 32547389, 2020). "In fact, we would like to speculate that besides repressing LAMB3 and CTNNAL1 expression, ZNF750 might also inhibit migration and invasion in breast cancer by repressing the expression of RAC1." (PMID 33298895, 2020). "Monitoring Rac1 level and targeting Rac1 may be utilized to predict and reverse the chemoresistance of breast cancers." (PMID 32193458, 2020). "In addition, multivariate Cox regression analyses demonstrated that Rac1 was an independent prognostic predictor for disease-free survival (DFS) (p = 0.036 for all breast cancer, and p = 0.013 for TNBC)." (PMID 32193458, 2020). "Given that ZNF750 is emerging as a crucial transcription factor that acts as tumour suppressor gene, here, we show that ZNF750 represses the expression of the small GTPase, Ras-related C3 botulinum toxin substrate 1 (RAC1) in breast cancer cell lines, by directly binding its promoter region." (PMID 33298895, 2020). "Interferon regulatory factor 4 binding protein (IBP, a Rho-family guanine nucleotide exchange factor for Rho family GTPases, including Rac1, RhoA and Cdc42) can mediate Rac1, RhoA and Cdc42 activation in breast cancer cells to regulate actin cytoskeleton rearrangement and MMP production." (PMID 30754684, 2019). "DOCK4‐mediated activation of Rac1 has been demonstrated to promote actin reorganisation and the formation of lamellipodia at the leading edge of breast cancer cells 19, as well as the formation of lateral filopodia and blood vessel lumen morphogenesis within tumour angiogenesis." (PMID 30426503, 2019). "Subsequently, Rab35 activates Rac1, which, in turn, promotes cell migration of breast cancer cells." (PMID 31035701, 2019). "Before comparing the detailed molecular mechanisms associated with KRT19 expression in colon and breast cancer cells, we hypothesized that whether KRT19 interacts with the β-catenin/RAC1 complex to regulate Wnt/Notch signaling crosstalk." (PMID 30650643, 2019). "Since RAC1 inhibitor NSC23766 is capable of combating breast cancer and lung cancer, the antitumoral effects of β-elemene may also involve the same pathway." (PMID 31068775, 2019). "From the sequencing results, we determined that RAC1 mRNA sequences were the same in both colon and breast cancer cells, whereas the KRT19 mRNA sequence showed a silent mutation, T→C (on 471 bp), in breast cancer cells alone." (PMID 30650643, 2019). "Our study is the first to reveal that SOX2 and NEDD9 may function as novel upstream regulators of Rac1/HIF-1α in hypoxic breast cancer cells." (PMID 31462898, 2019). "Mechanistically, in our previous study, we also found that KRT19 interacted with the β-catenin/RAC1 complex in breast cancer and was subsequently imported into the NUMB promoter in the nucleus, consequently regulating cancer properties through the Notch signaling pathway." (PMID 30650643, 2019). "It is therefore hypothesized that Rac1 activity may be influenced by intratumoral sex steroids in breast carcinomas." (PMID 29534468, 2018). "It has also been reported that Rac1 stimulates migration and invasion of breast cancer cells." (PMID 29534468, 2018). "Therefore, despite its crucial role in Rac1 activation and cell motility, P-Rex1 is dispensable for mitogenic or survival responses in breast cancer cells." (PMID 29983884, 2018).
breast carcinoma (continued). "It was therefore reasonably considered that ARHGAP15 may suppress the progress of breast carcinomas by attenuating the Rac1 pathway and may serve as better prognostic factor in breast carcinomas." (PMID 29534468, 2018). "Although a lot of studies have pointed out the pivotal roles of the Rac1 pathway in the progression of breast carcinomas, the clinical significance of ARHGAP15 has remained largely unknown in human breast carcinomas." (PMID 29534468, 2018). "Indeed, silencing P-Rex1 expression from luminal breast cancer cells severely affects Rac1 activation, actin cytoskeleton reorganization, ruffle/lamellipodia formation, and migration in response to growth factor stimulation." (PMID 29983884, 2018). "We suggest that by acting as a Rac1 inhibitor, this novel polypeptide may be useful for the treatment of breast cancer." (PMID 28549350, 2017). "Moreover, following the sequencing of human cancer cell lines, Rac1 P29S was also detected in the breast cancer cell line MDA-MB-157." (PMID 27442895, 2017). "In breast cancer cells, endogenous levels of Rac1, PI3K and PAK1 were all stimulated following treatment with epidermal growth factor (EGF) leading to increased migration, however in cells expressing a PAK1 kinase dead mutant this migratory response to EGF was significantly diminished." (PMID 27845911, 2017). "RAC1 was overexpressed or hyperactive in breast cancer tissues." (PMID 27902969, 2017). "Given the known role of Rac1 activity in cell migration of ER+ breast cancers and TNBCs, these results suggested that Rac1 may similarly be required for motility in HER2-amplified breast cancer cells." (PMID 28666462, 2017). "Our findings revealed that the novel WVLGE-containing polypeptide might serve as a breast cancer therapeutic through inhibition of Rac1 and Rac1-stimulated signaling pathways." (PMID 28549350, 2017). "In addition, MST3 promotes proliferation and tumorigenicity through the VAV2/RAC1 signal axis in breast cancer and RASAL2 activates RAC1 to promote triple-negative breast cancer progression." (PMID 28499439, 2017). "Rac1 is correlated with STAT family members that stimulate breast cancer progression." (PMID 28549350, 2017). "Deregulation of such processes are hallmarks of cancer and not surprisingly, altered Rac1 activity has been associated with malignant transformation in various types of cancer including breast cancer." (PMID 27058424, 2016). "Therefore, consistent with the requirement of P-Rex1 for MMP10 induction, these results indicate that in breast cancer cells MMP10 expression is regulated by Rac1 activation." (PMID 27351228, 2016). "β2-chimaerin is a Rac1-specific negative regulator and a candidate tumor suppressor in breast cancer but its precise function in mammary tumorigenesis in vivo is unknown." (PMID 27058424, 2016). "To test this hypothesis, we ectopically expressed β2-chimaerin, a Rac-specific GAP that accelerates GTP hydrolysis from Rac1 leading to its inactivation, as extensively demonstrated in cell-free systems and cell lines, including T-47D breast cancer cells." (PMID 27351228, 2016). "Rac1 activation is stimulated by hypoxia in breast cancer cells via PI3K/Akt signalling." (PMID 26769343, 2016). "Notably, we reported that HRG-induced activation of P-Rex1/Rac1 and motility via ErbB3 in breast cancer cells is mediated by transactivation of CXCR4, a G-protein-coupled receptor widely involved in metastatic dissemination." (PMID 27351228, 2016). "In our previous study, we established that HRG-induced activation of P-Rex1/Rac1 and motility in luminal breast cancer cells is mediated by transactivation of CXCR4, a G-protein-coupled receptor widely associated with breast cancer cell metastatic dissemination." (PMID 27351228, 2016). "RhoGDI2 associates with and negatively regulates Rac1 and Rac3 in breast cancer cells, but not RhoA, Cdc42, and RhoC, whereas it positively regulates Rac1 in human bladder cancer cells." (PMID 25901126, 2015).
breast carcinoma (continued). "While not specifically linked to Rictor in breast cancer cells, Rac1-mediated invasion and metastasis of breast cancer cells has been reported previously." (PMID 26132202, 2015). "it is demonstrated that RhoGDI2 inhibited Rac1 activity in MDA-MB-231 human breast cancer cells and mouse embryonic fibroblasts, whereas others showed RhoGDI2 acted as a positive regulator of Rac1 in T24 and UMUC3 human bladder cancer cells, H9c2 cardiomyoblast cells and ovarian cancer." (PMID 25901126, 2015). "Constitutively activated Rac1 promotes focal adhesions in breast cancer cells." (PMID 26156017, 2015). "Our findings demonstrate that while sustained Rac1 signaling (due to HER2 overexpression) may be a potent driver of transformation in human breast cancer, HACE1 is capable of tempering its downstream signaling ability." (PMID 25659579, 2015). "It is shown that Rac1-enhanced invasion of breast cancer cells could be diminished by the treatment of PI3K inhibitor, LY294002." (PMID 25361001, 2014). "The results of this study also suggest that the cell junctions of dormant MCF-7 breast cancer cells might be maintained in association with low Rac1 activity, which might be suppressed through potential high ROCK activity in dormant MCF-7 breast cancer cells." (PMID 24523903, 2014). "In addition, breast tumor cells from patients with recurrent disease had RAC1 expression at the plasma membrane, suggesting activation of RAC1, in patients with aggressive breast cancer." (PMID 24146998, 2013). "Future studies will determine whether any of these molecules contribute to the suppression of RhoA by BCAR3 and, in so doing, help to elucidate the mechanism by which BCAR3 affects the balance between Rac1 and RhoA signaling in invasive breast cancer cells." (PMID 23762409, 2013). "RhoGDI2 associates with and negatively regulates Rac1 and Rac3 in breast cancer cells, but not RhoA, Cdc42, and RhoC." (PMID 24185104, 2013). "In order to determine whether Rac1 protein might be a viable therapeutic target in breast cancer, we analysed its mRNA expression levels in published gene expression datasets." (PMID 22689141, 2012). "Over-expression of Rac1 and Rac3 GTPases has been noted in several small cohorts of breast cancers and it has been suggested that they may have a role in resistance to endocrine treatment." (PMID 22689141, 2012). "TRIO, a member of the HCCS24 gene set (genes above the blue line), is a guanine nucleotide exchange factor (GEF) that activates RAC1 (interaction 12) and stimulates the invasive behavior of some glioblastoma and breast cancers; inhibitors of this action of TRIO have been developed." (PMID 22570691, 2012). "In this study, we reported that hypoxia could induce HIF-1α and VEGF expression accompanied by Rac1 activation in MCF-7 breast cancer cells." (PMID 21980400, 2011). "Overexpression of Rac1 has been reported in breast carcinomas and may be involved in the invasion of gliomas and macrophages." (PMID 21961005, 2011). "Similarly, in the MCF10A breast cancer cell line HRAS activates PI3K pathway through Rac1 resulting in invasive phenotype." (PMID 21943101, 2011). "In this study, we investigated whether Rac1/ROS regulates PI3K/Akt and PAK1 signaling and is critically linked to EGF-mediated breast cancer cell migration." (PMID 23554696, 2011). "We wished to examine whether Rac1 influences HIF-1α expression in breast cancer cells under hypoxia." (PMID 21980400, 2011). "Previous studies demonstrated Akt could regulate the activation of GSK-3β, p70S6K1 and mTOR, and all of them were able to activate Rac1, suggesting that hypoxia stimulates Rac1 activation in breast cancer cells by activating PI3K/Akt signaling." (PMID 21980400, 2011). "We have also found that hypoxia can stimulate ROS generation in breast cancer cells, which may serve as an important mediator for hypoxia to stimulate Rac1 activation through the activation of PI3K and ERK signaling pathway." (PMID 21980400, 2011).
breast carcinoma (continued). "Overexpression of Rac1 correlates with progression of testicular, gastric, and breast cancer." (PMID 20822528, 2010). "RhoA, Rac1, Cdc42, and other family members are overexpressed and hyperactivated in early and late stage human breast tumors, and elevated RhoA and Rac1 expression correlates with breast cancer progression." (PMID 20860838, 2010). "Rho GTPases including RhoA, Rac1, and Cdc42 are elevated and hyperactivated in breast cancer." (PMID 20860838, 2010). "We can speculate in cells with mutated CK1ε that Wnt5a will predominantly signal via the Rac-1/JNK and NFAT pathways, thus promoting breast cancer cell invasion and tumor aggressivity." (PMID 20507565, 2010). "For instance, the oncogenic CRIPTO3 pseudogene is expressed in colon, breast and lung cancers, the human homologue of vaccinia virus H1 phosphotase gene clone 5 (hVH-5) pseudogene is expressed in breast cancer cell lines, and the rac1 pseudogene is expressed in brain tumors." (PMID 20625391, 2010). "Moreover, an increase of Rac1 and Pak1 activity or overexpression have been observed in breast cancer tissues and metastatic lymph nodes." (PMID 20426825, 2010). "Thus, although not directly evaluated in the present study, it is likely that A41 may offer a pharmacological mean of preventing or correcting RAC1-mediated resistance to breast cancer therapies." (PMID 40633540, 2025). "The significant association between high Rac1 expression and hormone receptors including ER status and Her2neu status in our study has been previously investigated, suggesting that a Rac1 inhibitor may be a promising treatment in endocrine-resistant breast cancer." (PMID 39118792, 2024). "Thus, such a mechanism could explain the involvement of Rac1 in the DS-dependent induction of oxidative stress in luminal breast cancer cells." (PMID 39062543, 2024). "Hence, common molecular mechanisms involving DOCK4/RAC1 may promote extravasation of breast cancer cells to the other metastatic sites." (PMID 38762624, 2024). "Taken together, Rac1 might serve as a promising therapeutic target in breast cancer." (PMID 39118792, 2024). "Interestingly, in breast cancer, the ratio of RAC1 and RAC1B can be used to determine if the tumor cells have a more epithelial or mesenchymal phenotype, where cells expressing more RAC1B have more epithelial properties and RAC1 expression is associated with a mesenchymal phenotype." (PMID 39001533, 2024). "Furthermore, inhibiting RAC1 can restore sensitivity to targeted therapy trastuzumab in breast cancer, suggesting that RAC1 inhibition could be an additional target for therapy in CRC." (PMID 39001533, 2024). "Racfamily small GTPase 1 (RAC1) may promote the migration of MCF-7 breast cancer cells." (PMID 37113771, 2023). "Thus, we conclude that the unified model with the upstream effector motif and the feedback from Cdc42 to Rac1 can explain both the simultaneous dynamics of Cdc42 and Rac1 in the breast cancer cell line (MDA-MB-231) and the delayed activation in the MEF cell line." (PMID 37371108, 2023). "In addition, PRKRA promoted breast cancer metastasis through SUMOylation of Rac1." (PMID 37484321, 2023). "Thus, we conclude that RAC1 may be the key effector of YAP1-induced invadopodia formation in breast cancer cells." (PMID 35773411, 2022). "We show that combined treatment of JQ1 (inhibitor of BRD4) and NSC23766 (inhibitor of RAC1) suppresses cell growth, clonogenic potential, cell migration and mammary stem cells expansion and induces autophagy and cellular senescence in molecular subtypes of breast cancer cells." (PMID 34803511, 2021). "Thus, RAC1 inhibitor suitable for clinical use may be a promising agent for treating endocrine-resistant breast cancer." (PMID 34373577, 2021). "RAC1 is expressed in both estrogen receptor alpha (ER)-positive and ER-negative breast cancer (BC) cells." (PMID 34373577, 2021).